NAPA (NSF attachment protein alpha)
Description:
Required for vesicular transport between the endoplasmic reticulum and the Golgi apparatus (Probable). Together with GNA12 promotes CDH5 localization to plasma membrane.
Synonyms: SNAPA
Tractability: Antibody: UniProt places it where antibodies can reach, with high confidence; its Gene Ontology location is reachable by antibodies, with medium confidence. PROTAC: ubiquitination databases record sites on it; its protein half-life has been measured.
Gene: Protein-coding gene on chromosome 19 (47,487,637 to 47,515,091, reverse strand). Ensembl gene ENSG00000105402.
Subcellular location: Cell membrane
Subcellular location (Human Protein Atlas): Cytosol
Pathways (Reactome):
Vesicle-mediated transport: COPI-dependent Golgi-to-ER retrograde traffic; COPI-mediated anterograde transport; COPII-mediated vesicle transport; Golgi Associated Vesicle Biogenesis; Intra-Golgi traffic; Retrograde transport at the Trans-Golgi-Network
Gene Ontology:
Molecular function: protein binding; protein-containing complex binding; SNARE binding; soluble NSF attachment protein activity; syntaxin binding
Biological process: intra-Golgi vesicle-mediated transport; intracellular protein transport; membrane fusion; regulation of synaptic vesicle priming; SNARE complex disassembly; synaptic transmission, glutamatergic; protein-containing complex disassembly; response to hyperoxia; synaptic vesicle priming
Cellular component: extracellular exosome; membrane; cytosol; synaptobrevin 2-SNAP-25-syntaxin-1a complex; terminal bouton; cytoplasmic vesicle; dendrite; glutamatergic synapse; lamellar body; mitochondrion; neuromuscular junction; perikaryon; plasma membrane; postsynapse; postsynaptic membrane; presynapse; presynaptic active zone membrane; presynaptic membrane; synaptic membrane; synaptic vesicle
Genetic constraint (gnomAD): Loss-of-function variants: 18 observed, 49.63 expected, observed/expected ratio (o/e) 0.36, 90% interval 0.25 to 0.54. The upper end of that interval is the gene's LOEUF score, 0.54, which puts it in group 2 of 6, group 1 being the genes least tolerant of losing a copy. Missense variants: 315 observed, 400.09 expected, observed/expected ratio (o/e) 0.79, 90% interval 0.72 to 0.86. Synonymous variants: 152 observed, 155.3 expected, observed/expected ratio (o/e) 0.98, 90% interval 0.86 to 1.12.
Homologues: Orthologues: chimpanzee NAPA (100% identical), macaque NAPA (98% identical), mouse Napa (98% identical), rat Napa (98% identical), guinea pig NAPA (98% identical), rabbit NAPA (98% identical), dog NAPA (97% identical), pig NAPA (94% identical), tropical clawed frog napa (91% identical), zebrafish napab (84% identical), zebrafish napaa (75% identical), Drosophila melanogaster alphaSnap (62% identical), and 1 more. Paralogues in human: NAPB (84% identical), NAPG (26% identical).
Diseases named in the same sentence as NAPA in open-access papers:
NAPA is named in the same sentence as 29 diseases in open-access papers, as found by Europe PMC text mining. Sharing a sentence is not in itself a finding about the gene and the disease. The quoted sentences say what the papers report.
gastritis (4 papers, 2012 to 2020). Inflammation of the stomach. "The analysis results of H. pylori virulence genes revealed a specific association between the H. pylori napA virulence gene and H. pylori-related gastritis." (PMID 32908495, 2020). "H. pylori napA virulence gene could serve as a biomarker for the development of diagnostic kits to foresee the evolution of H. pylori-associated gastritis." (PMID 32908495, 2020). "It was found that 94% of patients with gastritis were positive for the H. pylori napA gene that is one of the most important virulence factors and taking a role in bacterial colonization and gastric inflammation." (PMID 32908495, 2020). "By histological examination, this study observed the NapA immunized mice had significantly lower severity of gastritis than the controls treated with PBS." (PMID 31461854, 2019). "NapA has been recognized as a key modulator in H. pylori-induced gastritis and has been proposed as a protective antigen and promising vaccine candidate against H. pylori infections." (PMID 23101660, 2012). "In this present study, it was aimed at evaluating the association between seven important H. pylori virulence genes, vacA, cagA, oipA, hpaA, babA, napA, dupA, ureA, and ureB, with the clarithromycin and fluoroquinolone resistance in H. pylori-infected patients with gastritis." (PMID 32908495, 2020). "Herein, we report that the relationship between the H. pylori napA gene and gastritis." (PMID 32908495, 2020). "94% of patients with gastritis were positive for H. pylori napA gene." (PMID 32908495, 2020). "According to the gastritis grading scores, NZ-Δsp-napA group displayed the lowest inflammation level among the H. pylori challenged groups, whereas the NapA+LtB immunized mice had significantly higher inflammatory lesion than the mice treated with NapA alone (p < 0.05)." (PMID 31461854, 2019). "However, the prevalence of H. pylori napA virulence factor was significantly higher in patients with ulcer than gastritis." (PMID 26287606, 2015). "Notably, NZ-Δsp-napA+ltB group showed much more severe gastritis than NZ-Δsp-napA group." (PMID 31461854, 2019).
Lyme borreliosis (2 papers, 2014 to 2021). "Taken together, our immunoblotting and immunofluorescence studies confirm that NapA is a PAP in the Lyme disease spirochete." (PMID 33984073, 2021).
abscesses (1 paper, 2019). "During the process, the activated neutrophils and microphages start degranulation when contacting foreign components like LtB and NapA, and form abscesses and epithelial erosions." (PMID 31461854, 2019).
allergic disease (1 paper, 2018). An immune response that occurs following re-exposure to an innocuous antigen, and that requires the presence of existing antibodies against that antigen. "As reported, NapA has considerable efficacy on alleviating Th2-based allergic diseases like asthma." (PMID 29691472, 2018). "Similarly, for other Th2 predominant allergic diseases, immunotherapies might also be established by using H. pylori NapA." (PMID 29691472, 2018).
Arthritis (1 paper, 2021). Inflammation of a joint. "Therefore, the coordinated effect of both NapA and PG within the synovial tissue during later stages could exacerbate arthritis severity through the chemotactic properties of NapA-PG." (PMID 33984073, 2021).
chronic gastritis (1 paper, 2013). Inflammation of the stomach that is chronic in nature. "The detection of GGT, NapA and Slt may explain the chronic gastritis as characterized by the occurrence of inflammatory cells in the gastric mucosa observed of some infected felines." (PMID 23940723, 2013).
Helicobacter infection (1 paper, 2018). "One possible solution might be using certain H. pylori components, like NapA, to replace the Helicobacter infection for depression of Th2 responses." (PMID 29691472, 2018).
lung adenocarcinoma (1 paper, 2024). A carcinoma that arises from the lung and is characterized by the presence of malignant glandular epithelial cells. "In cases of lung adenocarcinoma, under malignant conditions NapA may be regulated by TTF-1, where low levels of NapA lead to TGF-β induced neoplastic cell proliferation." (PMID 38994972, 2024). "Current clinical algorithms for the diagnosis of human lung adenocarcinoma typically require positivity of stains for thyroid transcription factor 1 (TTF-1) and aspartic proteinase Napsin A (NapA), and negativity of stains for either p40 or p63." (PMID 38994972, 2024). "Specifically, our cells are TTF-1 and NapA positive and p40 negative, and when used to generate orthotopic tumors, exhibit histology typical of solid human lung adenocarcinoma." (PMID 38994972, 2024).
ovarian tumors (1 paper, 2013). "Therapy by using the gene NAPA and the protein, Napsin A could be one option of many for treatment of clear cell ovarian tumors from of a variety of tissues in the future." (PMID 24191930, 2013).
pericarditis (1 paper, 2026). An inflammatory process affecting the pericardium. "Among them, elevated levels of NEU1, GDNF, and LAT increased the risk of pericarditis, whereas higher levels of CASP8, ZFYVE27, and NAPA decreased the risk of pericarditis." (PMID 41674924, 2026).
rheumatoid arthritis (1 paper, 2025). A chronic, systemic autoimmune disorder characterized by inflammation in the synovial membranes and articular surfaces. "NapA is a potent Th17 cell activator, a T cell subset implicated in the persistence of inflammation in rheumatoid arthritis (RA)." (PMID 40732111, 2025).
small cell carcinoma (1 paper, 2022). A neuroendocrine carcinoma composed of small malignant cells which are often said to resemble "oat cells" under the microscope. "Methods: 44 CoLCNECs: 26 with adenocarcinoma (CoADC), 7 with squamous cell carcinoma (CoSQC), 3 with small cell carcinoma (CoSCLC), 4 with atypical carcinoid (CoAC) and 4 napsin-A positive LCNEC (NapA+), were assessed for alterations in 409 genes and transcriptomic profiling of 20,815 genes." (PMID 36230576, 2022).
ulcer disease (1 paper, 2015). A lesion on the surface of the skin or a mucous surface, produced by the sloughing of inflammatory necrotic tissue. "However, we identified a statistically significant correlation (p = 0.007) between napA gene and H. pylori-associated ulcer disease." (PMID 26287606, 2015). "Within all virulence factors that we tested, we identified a correlation between the presence of napA virulence gene and ulcer disease as a first data." (PMID 26287606, 2015). "However, we could not find any research like in our study in which the relationship between the napA gene and ulcer disease was showed clearly." (PMID 26287606, 2015).
viral infection (1 paper, 2021). "Finally, dSpace analysis identified several genes (CCL2, OASL, CASP7, TMEM123, MAFB, VRK2, UBE2L6, NAPA) higher in patients with mild viral infection than those with severe viral infection or HCs." (PMID 33765435, 2021).
infection (13 papers, 2013 to 2025). The state of being infected such as from the introduction of a foreign agent such as serum, vaccine, antigenic substance or organism. "BabA2, HpaA, and NapA are important adhesins of H. pylori that promote the infection of cells by H. pylori." (PMID 40607440, 2025). "To address this question, we collected the luminal content and the mucus layer of S. Tm-infected gnotobiotic mice 1 and 2 days after infection, and assessed mRNA levels of pflB, fdoG, fdnG, and napA by RT-qPCR." (PMID 37498116, 2023). "NapA also has the function of attracting neutrophils to the site of infection and induces a respiratory burst of infiltrating neutrophils, which contributes to cellular oxidative stress and DNA damage." (PMID 35626358, 2022). "NapA, which activates neutrophils, plays a major role in recruiting human neutrophils and monocytes to the infection site." (PMID 33649116, 2021). "Earlier studies have shown that napA is dispensable for mouse infection but required for tick survival." (PMID 33984073, 2021). "The results showed that the oral vaccination with the L. lacitis-delivered NapA was capable of significantly reducing the bacterial load in the stomachs of the mice challenged with H. pylori, but unable to protect the mice from infection." (PMID 29691472, 2018). "Further, a Salmonella napA mutant defective in periplasmic nitrate reduction shows a growth defect in the lumen of the colon in a mouse model of infection." (PMID 28224117, 2017). "Positive regulation of NapA by σ54 would be helpful for prolonged survival of H. pylori in water, which may play an important role in H. pylori transmission and infection." (PMID 24015282, 2013). "As such functions are also important during pathogenic interactions, we propose that these and not NapA ROS-detoxification roles, might be relevant for NapA critical virulence roles, specially when conidia mediate the infection process." (PMID 28424666, 2017). "The relatively strong inflammation and immune responses induced by Δomp18 infection in C57BL/6 mice's gastric systems may contribute to its defective colonization and attribute to the high expressions of virulence factors CagA and NapA in the Δomp18 strain induced by IFN-γ." (PMID 25945338, 2015).
tumor (3 papers, 2012 to 2024). "This agrees with our results indicating the upregulation in the tumor margin of both CTSD and NAPA, which are present in the phagosome maturation pathway." (PMID 35512017, 2022).
cancer (1 paper, 2018). A tumor composed of atypical neoplastic, often pleomorphic cells that invade other tissues. "In future, the engineered L. lactis expressing NapA might be applied as an immune modulatory agent, for instance, in treatment of certain immune dysregulation and carcinomas." (PMID 29691472, 2018).
nervous system diseases (1 paper, 2022). "Among genes of module-3, NAPA showed the strongest association (60%), SCFD1, and STX5(30–40%) suggesting their possible role in the etiology of nervous system diseases." (PMID 34918006, 2022).
NAPA also shares sentences with these, for which no sentence is quoted: Hydrocephalus (3 papers); pancreatic cancer (2); adenocarcinoma (1); Allergy (1); chronic pancreatitis (1); colitis (1); gastrointestinal tract cancers (1); hemorrhage (1); inflammation (1); ovarian carcinoma (1); squamous cell carcinoma (1).